MTF1 (metal regulatory transcription factor 1)
Diseases named in the same sentence as MTF1 in open-access papers (continued):
Sharing a sentence is not in itself a finding about the gene and the disease.
infection (3 papers, 2021 to 2023). The state of being infected such as from the introduction of a foreign agent such as serum, vaccine, antigenic substance or organism. "We confirmed by qPCR that Vta3 reduces MTF1 expression in xylem sap as prerequisite for further investigation of possible Mtf1 functions in the pathogenic fungus V. dahliae during infection of tomato plants." (PMID 36716333, 2023). "At the end of the infection cycle, Mtf1 initiates the formation of resting structures that allow the fungus to survive in the soil and later to re-infect host plants." (PMID 36716333, 2023). "Vta3 delays Mtf1 action, which triggers plant immune responses and is required for late stages of infection." (PMID 36716333, 2023). "Taken together, these data demonstrate that infection by V. dahliae requires an intact MTF1 gene to activate defense responses in tomato plants." (PMID 36716333, 2023). "The levels of pipecolic and salicylic acids functioning in tomato defense signaling against (hemi-) biotrophic pathogens depend on the presence of MTF1, which promotes the formation of resting structures at the end of the infection cycle." (PMID 36716333, 2023). "Furthermore, Mtf1 promotes microsclerotia formation enabling fungal survival in the soil and re-infection of host plants." (PMID 36716333, 2023). "In future studies, it will be interesting to compare the expression patterns of ELV1, MTF1 and VTA3 during infection of tomato plants by V. dahliae." (PMID 36716333, 2023).
MTF1 also shares sentences with these, for which no sentence is quoted: retinoblastoma (3 papers); bladder cancer (2); lung squamous cell carcinoma (2); pheochromocytoma (2); thyroid cancer (2); adrenocortical carcinoma (1); alcoholic hepatitis (1); alcoholic liver diseases (1); Arthritis (1); autism (1); bladder urothelial carcinoma (1); bone cancer (1); brain cancer (1); breast invasive carcinoma (1); cervical cancer (1); colon cancer (1); coronary heart disease (1); diffuse large B-cell lymphoma (1); endocervical adenocarcinoma (1); esophageal carcinoma (1); eye cancer (1); glioblastoma multiforme (1); head and neck squamous cell carcinoma (1); head and neck tumor (1); Infertility (1); kidney chromophobe (1); leukemia (1); liver disease (1); lymphoid neoplasm (1); myelodysplastic syndrome (1).
A further 22 diseases each share a sentence with MTF1 in 1 paper.